MDM2 (MDM2 proto-oncogene)
Diseases named in the same sentence as MDM2 in open-access papers (continued):
Sharing a sentence is not in itself a finding about the gene and the disease.
gastric cancer (continued). "In addition, there is a joint effect of MDM2 SNP309G/G allele and H. pylori infection for the development of gastric carcinoma, which may attribute to H. pylori LPS." (PMID 23506213, 2013). "Therefore, our aim is to investigate whether MDM2 SNP309 (T > G) is associated with susceptibility and prognosis to gastric carcinoma in Chinese patients." (PMID 23506213, 2013). "Consistently, in CRC HT29 and gastric cancer HGC-7901 cell lines, knockdown NFATc1 simultaneously suppressed the transcriptional activity of MDM2." (PMID 41203626, 2025). "In gastric cancer progression, NAT10 modifies MDM2 mRNA with ac4C acetylation to stabilize MDM2 mRNA, resulting in its up-regulation and down-regulation of p5346." (PMID 38459019, 2024). "In cervical cancer and gastric cancer, RPL11 contributed to tumorigenesis by translocating to the cytoplasm and further binding to MDM2." (PMID 36869281, 2023). "Our previous screening of the genes that are regulated by GLA in gastric cancer cells revealed that Mdm2 and RNF6 were the most downregulated genes, among others, in response to GLA treatment in gastric cancer cells." (PMID 35814430, 2022). "We have now studied the role of FOLRα in gastric cancer and found that a signaling axis comprising FOLRα, prohibitin 2 (PHB2), and murine double minute 2 (MDM2) contributes to chemotherapy resistance." (PMID 34185411, 2021). "In consistent with above statement, CA10 treatment reduced the protein expression of CDC2, Cyclin B1 and MDM2, this further emphasizes that CA10 can inhibit the aggressive potential of gastric cancer cells through G2/M cycle arrest." (PMID 29254150, 2017). "In addition, our meta-analysis also indicated that the MDM2 SNP309G/G genotype was associated significantly with an increased risk of gastric carcinoma, and provided further evidence indicating an association between this functional polymorphism and gastric carcinoma susceptibility." (PMID 23506213, 2013). "Mdm2 and RNF6 are classified as oncogenes in various types of cancer, including gastric cancer." (PMID 35814430, 2022). "Most ligases evaluated were not highly present in tumors except for MDM2 in breast, lung, prostate and gastric cancer." (PMID 35249548, 2022). "This suggests that the G/G genotype of MDM2 SNP309 might, therefore, be predictive of poor survival in gastric carcinoma patients." (PMID 17537232, 2007). "Moreover, there has been no report on the association between MDM2 SNP309 (T > G) and survival of gastric carcinoma patients in Chinese patients." (PMID 23506213, 2013). "Thus our results suggest that targeting of FOLRα alone by farletuzumab may not be sufficient to downregulate MDM2 function in gastric cancer and that the therapeutic efficacy of farletuzumab, even in combination with chemotherapy, may be limited." (PMID 34185411, 2021).
colon carcinoma (83 papers, 2007 to 2025). "We further observed notable increases in expression levels of PCNA, β-catenin, and MDM2 widely recognized as cell proliferation markers associated with colon cancer in the AOM/DSS-treated mice." (PMID 39893188, 2025). "MDM2 downregulation in HT-29 colon cancer cells was associated with RB1 upregulation upon 5-ISA-fortified lettuce extracts, which provides a link to the epigenetic regulation of tumor suppressor genes by RB/MDM2 pathway." (PMID 36296971, 2022). "In our present study, MDM2 downregulation in HT-29 colon cancer cells was associated with RB1 upregulation upon 5-ISA-fortified lettuce extracts as compared to control lettuce." (PMID 36296971, 2022). "In clinical samples, increase in MDM2 gene amplification and cytoplasmic expression are observed in colon cancer, which is associated with advanced cancer staging." (PMID 30271790, 2018). "Previously, it was shown that reduced levels of Mdm2 in Mdm2 hypomorphic mice inhibited colon tumor development from loss of adenomatous polyposis coli (Apc)." (PMID 23029416, 2012). "Similarly in activin treated SMAD4 null SW480 colon cancer cells, NFkB inhibition with wtNBD peptide caused reduced expression of MDM2 paralleled with increased p21 protein expression." (PMID 28418896, 2017). "Moving forward, we recommend further mechanistic studies in chronic colitis models, exploration of Resveratrol’s clinical translation, and investigation of MDM2-targeted therapies for both UC and colon cancer." (PMID 40371345, 2025). "TCGA analysis revealed that MDM2 expression was significantly reduced in colon cancer patients, and high MDM2 expression correlated with better survival outcomes." (PMID 40371345, 2025). "Inhibiting circ-MDM2 reduced MDM2 and p21 protein levels and caused G1/S phase cell cycle arrest in HCT116 colon cancer cells." (PMID 39831201, 2024). "Colon Cancer: Fluspirilene can disrupt the interaction by filling in the hydrophobic pocket and binding the site of MDM2." (PMID 35563397, 2022).
colon carcinoma (continued). "In the presence of EGFR, MDM2 can bind to peroxisome proliferator-activated receptor-gamma (PPARγ) and regulate the ubiquitination of PPARγ protein in colon cancer cells." (PMID 36230661, 2022). "It has been documented that after addition of EGFR, MDM2 can bind to PPARγ and regulate the ubiquitination of PPARγ protein in colon cancer, and that MDM2 silencing can increase the level of PPARγ, which is further verified in bladder cancer." (PMID 36230661, 2022). "MDM2 inhibition was shown to induce growth arrest and DNA breakage in colon tumor in mouse and human CC cells." (PMID 32423468, 2020). "This was attributable to the incomplete or short list of MDM2 correlated genes in both breast and colon cancer." (PMID 33400740, 2020). "We evaluated the association of hnRNPA2B1 with BCL2L1, BCL2, MDM2, cMYC, CD44, CDK6, cJUN, and TXNP in HCT116 colon cancer cells treated with 70 μg/ml of the crude extract." (PMID 33163396, 2020). "MDM2 and MDM2 overexpression is a candidate biological link between T2D and colon cancer development." (PMID 33117687, 2020). "MDM2 overexpression is a candidate biological link between type 2 diabetes and colon cancer development." (PMID 30271790, 2018). "Treatment of colon cancer cells with activin led to an increase in MDM2 protein expression after 24h of stimulation that was further augmented by p65 overexpression." (PMID 28418896, 2017). "In conclusion, in colon cancer cell migration, activin utilizes NFkB to induce MDM2 activity leading to the degradation of p21 in a PI3K dependent mechanism." (PMID 28418896, 2017). "The variant is in complete linkage disequilibrium with MDM2 SNP309 (rs2279744) and has previously been found associated with an increased risk of colon cancer." (PMID 28158999, 2017). "Do MDM2 and A20 play redundant roles in human colon cancer and colon polyps is an interesting point to be further investigated." (PMID 24099634, 2013).
colon carcinoma (continued). "In addition, a primary colon carcinoma was shown to have a point mutation at codon 12 in exon 1β, which was thought to impair the binding of ARF to MDM2 and subsequently MDM2 nuclear translocation." (PMID 34065345, 2021). "Third, the novel MDM2-recruiting PROTAC remained cytotoxic in the BRD4-KO colon cancer cells." (PMID 32978368, 2020). "Recent studies have demonstrated that combination treatment with MDM2 inhibitor and Bcl-2 inhibitor results in synergistic anti-tumor activity compared with the respective single-agent treatments in acute myeloid leukemia and colon cancer cells." (PMID 30816344, 2019). "Interestingly, we found that pretreatment of colon cancer cells with wtNBD peptides reduced the activin-induced increase in MDM2 mRNA expression in a dose dependent manner." (PMID 28418896, 2017). "DANCR may affect colon cancer cell growth and metastasis through the miR-518a-3p/MDM2 axis." (PMID 38002356, 2023). "Interestingly, our results revealed an increased risk of left-sided but not right-sided colon cancer with respect to MDM2 SNP55 status." (PMID 27624283, 2016). "In both HCC and colon cancer, PXR promotes MDM2 auto-ubiquitination, impairing MDM2-mediated ATF3 protein degradation." (PMID 38137461, 2023). "DANCR is highly expressed in colon cancer tissues and cell lines, and silencing DANCR inhibits the proliferation, survival, and metastasis of colon cancer via the DANCR/miR-518a-3p/MDM2 axis." (PMID 38002356, 2023). "Strikingly, the result showed that PXR reduced the MDM2 half-life in colon cancer cells, and PXR increased endogenous ubiquitination of MDM2." (PMID 35372071, 2022). "Treatment of HCT116 colon cancer cells with 70 μg/ml of C. orbiculata extract resulted in an increase in the co-precipitation of hnRNPA2B1 with BCL2L1, BCL2, MDM2, cMYC, CD44, CDK6, and cJUN mRNA." (PMID 33163396, 2020). "In summary, we show that in colon cancer, activin activates NFkB via PI3K increasing migration via p21 regulation through the MDM2 ubiquitin ligase." (PMID 28418896, 2017).
colon carcinoma (continued). "In contrast, TGFB did not induce MDM2 protein expression in colon cancer cells nor did it further enhance MDM2 expression in the p65 overexpressing cells." (PMID 28418896, 2017).